TNF (tumor necrosis factor)
Diseases named in the same sentence as TNF in open-access papers (continued):
Sharing a sentence is not in itself a finding about the gene and the disease.
fungal infections (continued). "TNF-α is a potent activator of endothelial cells which helps in the migration of monocytes and neutrophils to the sites of infection, and it is also required for the clearance of fungal infection." (PMID 36983458, 2023). "C-type lectins receptors were shown to recognize fungal cell wall β-glucan and mannan, activate downstream signaling pathways, promote immune cells to secrete IFN-γ, IL-6, TNF-α, and other pro-inflammatory cytokines, and initiate adaptive immune responses to clear fungal infection." (PMID 36079904, 2022). "Twenty-eight days after starting the anti-TNFα antibody, mice had significantly increased lung and spleen fungal burdens compared to the controls, indicating that these animals were starting to lose control of the fungal infection." (PMID 35174101, 2021). "However, inhibition of the TNF-alpha pathway results in a predisposition to severe infections including histoplasmosis, which is the commonest invasive fungal infection in patients on TNF-alpha therapy." (PMID 34209280, 2021). "We demonstrated that peptidorhamnomannan leads to TNF-α production in J774 macrophages for 1, 2 and 3 h of incubation, suggesting that this glycoconjugate may have a beneficial role in the response to fungal infections." (PMID 32762645, 2020). "Hence, cortisol plays an important role during fungal infection through its ability to suppress the host immune system by downregulating TNF-α, IFN-γ, and IL-2 cytokines." (PMID 32801570, 2020). "Improved tolerance may be due to decreased expression of pro-inflammatory cytokines TNF-α and IL-1β found in mice with invasive fungal infections treated with AmB-IL when compared with dextrose infusions of AmB-DOC." (PMID 31906268, 2020). "There may be a potential role that TNF-alpha inhibitors can play in mitigating IRIS related to disseminated endemic fungal infections." (PMID 30662827, 2018). "Endemic fungal infections are a significant problem for patients on TNF-alpha inhibitors." (PMID 30662827, 2018). "In addition, knocking down c-Jun and c-Fos in macrophages decreases H. capsulatum-induced TNF and IL-6 response, highlighting the role of AP-1 in host defense against fungal infections." (PMID 26132276, 2015). "IL-22 typically protects against bacterial and fungal infections, but recent findings suggest that it amplifies the effects of other cytokines that are known to be involved in ocular inflammation, such as interleukin 1-β (IL-1β), tumor necrosis factor-α (TNF-α), interleukin 6 (IL-6), and IL-17." (PMID 38247834, 2024). "The decrease of proinflammatory cytokines could be associated with a reduction of infection and absence of hyphae, once the marked release of IL-6 occurs due to the exposition of hyphal fragments of A. fumigatus TNF plays an important role in host immune defense against invasive fungal infections." (PMID 34249777, 2021). "In our group, we could recently demonstrate a similar effect in monocytes upon fungal infection, reporting the down-regulation of Candida albicans-induced TNFα, IL-6 and IL-12B expression in response to all-trans retinoic acid (atRA), the active metabolite of vitamin A21." (PMID 28094291, 2017). "In contrast, during the chronic phase of fungal infection, the recruitment of neutrophils induces an uncontrolled immune reaction, leading to a severe tissue inflammatory pathology due to the excessive release of IL-17, TNF-α and enzymes contained in their granules." (PMID 27690127, 2016). "TNF-α blockade is associated with fungal infections, but no Acremonium spp." (PMID 22567476, 2011). "MAIT cells play a crucial role in controlling bacterial and fungal infections through their production of cytokines, including IFN-γ, TNF-α, and IL-17, as well as cytotoxic molecules such as Granzyme B and Perforin." (PMID 40025566, 2025). "In both fungal infections, the immune response includes a Th1 response mediated by CD4, CD8, and NK cells, with TNF-α secretion also by macrophages, neutrophils, and dendritic cells." (PMID 41156648, 2025).
fungal infections (continued). "Perhaps these cells compensate for the decreased TNF-α produced by neutrophils during treatment with BTK inhibitors, resulting in less established fungal infections in the periphery." (PMID 38713531, 2024). "CD8+ T-cells, on the other hand, act to control fungal infection either by cell-mediated cytotoxic activity or by producing IFN-γ and TNF." (PMID 34359982, 2021). "Of note, expression and secretion of TNF-α and IL-1β in NLC were strongly affected by ibrutinib mimicking fungal infection." (PMID 32983178, 2020). "HIF-1α inhibition increased TNF and IL-10 levels after Candida infection, and it has been previously shown that HIF-1α controls progression of fungal infections by limiting IL-10 production." (PMID 32999407, 2020). "IL17A binding to IL-17RA/IL17RC heterodimers leads to the production of cytokines and chemokines, such as tumor necrosis factor a (TNF-α), IL-6, CXCL8, and CXCL1, involved in mechanisms of the host defense against extracellular bacterial and fungal infections." (PMID 32373132, 2020). "Cytokines used as immunomodulatory agents in fungal infection include colony-stimulating factors (CSFs), Interferon-Gamma (IFN-γ), TNF α and Interleukins." (PMID 33042859, 2020). "The expression of mRNAs for Interleukin-1β (IL-1β), TNFα, and TLR4 were evaluated in the corneas of the mice with fungal infection and the control corneas by real-time PCR." (PMID 31285488, 2019). "The accumulated evidence implicates that TLR4 and TNFα are important in the pathogenesis of fungal infection, hence, we investigated if SAHA affects fungal keratitis due to the inhibition of key cytokines-TNFα and the inactivation of TLR4." (PMID 31285488, 2019). "Toll-like receptors (TLR2, TLR4), pro-inflammatory cytokines [tumor necrosis factor, interleukin 6 (IL-6), IL-1, and interferons], nuclear factor κB signaling, and HMGB1 were among top upstream regulators of the targets in fungal infection." (PMID 31969817, 2019). "In fungal infections, a mixed TH1/TH17 immune response confers resistance through the secretion of cytokines such as IFN-γ, TNF-α and IL-17A, which activate neutrophils and macrophages for fungal killing and clearance." (PMID 29520092, 2018). "For the control group, it was evident that the expression of both TNF-α and MMP-9 increased significantly in the stromal layer during the course of the fungal infection." (PMID 29403058, 2018). "Since monocytes represent a major source of pro-inflammatory cytokines such as TNF-α or IL-6 during infection, this may explain the prolonged pro-inflammatory response and sustained inflammation in organs such as brain, lung and eye in neonates suffering from bacterial or fungal infection." (PMID 27870876, 2016). "To investigate CIN’s immunomodulatory mechanism, we analyzed Dectin-1 signaling components (Dectin-1, SYK, and CARD9), NF-κB activation, and proinflammatory cytokines (TNF-α and IL-1β) in RAW264.7 and PMA-differentiated THP-1 macrophages during a 24-h fungal infection." (PMID 41031111, 2025). "Fungal infections inducing the Th-1 cytokines (e.g. IFN-γ, TNF-α, and IL-2) in the serum of infected individuals have been reported and these are involved in macrophage activation, nitric oxide production, and cytotoxic T lymphocytes proliferation to enhance phagocytosis and fungal clearance." (PMID 38787374, 2024). "While these results are encouraging, the use of TNF-α during fungal infections in patients treated with a BTK inhibitor is not feasible, given the numerous off-target effects and induction of severe endotoxic shock." (PMID 38713531, 2024). "Compared to TNF-α and IL-10, CCL3/MIP-1⍺ plays an important role in recruiting various cells such as monocytes, macrophages, lymphocytes, and eosinophils via the CCR1 or CCR5 receptor, thereby strengthening the immune response against a fungal infection." (PMID 38967888, 2024).
fungal infections (continued). "In addition, the mRNA expression of IL-1β, TNFα and TLR4 was significantly increased in the corneas with fungal infection, compared with the control group in which only DMSO injection was administrated (P < 0.05)." (PMID 31285488, 2019). "We found that FK506 may reduce the infiltration of inflammatory cells by suppressing the expression of proinflammatory cytokines such as TNFα and IL-1β and downregulating the expression of TREM-1 at an early stage of fungal infection in corneas." (PMID 25464008, 2014). "Likewise, there were no cases of histoplasmosis recorded in the BIOBADASER, a large safety registry of a cohort of patients with RA treated with TNF-α inhibitors followed in Spain, a country where histoplasmosis is not considered an endemic mycosis." (PMID 38065857, 2023). "IL-17 can stimulate the generation of various cytokines (such as TNF and IL-6), vascular endothelial growth factor (VEGF), and chemokines (CXCL1 and CXCL8), increase AMP expression, and promote keratinocyte proliferation, which may essentially lead to the clearance of cutaneous fungal infection." (PMID 38022599, 2023). "However, we could not rule out the possibility that the superimposed fungal infection might have played a role in the induction of TNF-α in this patient." (PMID 16022777, 2005). "Additionally, M1‐type cytokines, such as IL‐4, IL‐12, IL‐6, IL‐23, TNF‐α, IL‐1β, and IFN‐β, were slightly elevated upon stimulation by fungi, but no statistical difference was detected between the two fungal infection groups." (PMID 37211685, 2023).
leishmaniasis (138 papers, 2006 to 2025). Infectious disease that is transmitted through the bite of hematophagous female phlebotomine sand flies. "KEGG analysis indicated that the candidate DEGs were predominantly enriched in pathways such as Leishmaniasis, TNF signaling pathway, Kaposi sarcoma-associated herpesvirus infection, and MAPK signaling pathway." (PMID 41312369, 2025). "A number of evidence indicates that treatment with biologics, mainly TNF-α inhibitors predispose to the development of clinically evident leishmaniasis in patients with IMID." (PMID 40993715, 2025). "Studies using C57Bl/6 mice, which are normally resistant to leishmaniasis, become susceptible to the disease when deficient in soluble TNF, even developing a Th1 response, presenting a high parasite load, and persistent lesions." (PMID 41156732, 2025). "Although TNF-α has been associated with host protection in leishmaniasis due to induction of iNOS in mononuclear phagocytes in association with IFN-γ, it has also been related to disease severity and enhanced lesion sizes." (PMID 36839479, 2023). "This particular cytokine in leishmaniasis is so important that TNF-α blocker-based therapy seems to be associated with a higher risk of infections, at times with a worse outcome." (PMID 35992172, 2022). "The role of drugs, especially anti-TNF and new antineoplastic agents, in the risk of developing leishmaniasis is controversial." (PMID 31931865, 2020). "Forty-nine cases of anti-TNF-α–associated leishmaniasis are published in the literature, 28 with cutaneous leishmaniasis, 16 with visceral leishmaniasis, and 5 with mucocutaneous leishmaniasis." (PMID 32642311, 2020). "The increase in the use of TNF-α antagonist has been associated with the emergence of new cases of leishmaniasis." (PMID 31469834, 2019). "Leishmaniasis has been associated with the use of TNF-α blockers, but only few cases have been reported in the literature, mainly in the Mediterranean basin." (PMID 31469834, 2019). "Clinical and microbiological characteristics of patients with leishmaniasis associated to TNF-α antagonist treatment in the Mediterranean Basin." (PMID 31469834, 2019). "Although there is scarce information for its recommendation, etanercep or certolizumab have been suggested as a therapeutical option instead of re-introducing other anti-TNF-α monoclonal antibodies due to its possible lower risk of reactivating leishmaniasis." (PMID 31469834, 2019). "For example, in experimental leishmaniasis, insufficient TNF-α is associated with progressive disease and death." (PMID 28000706, 2016). "We alsoreviewed all similar cases from Europe reported in the literature, and we discuss theimplications of leishmaniasis in the setting of anti-TNF therapy, which is associatedwith increased risk for opportunistic infections." (PMID 19523302, 2009). "In Leishmaniasis, TNFα enhances disease pathogenesis, but TNFα-deficient mice can exhibit a compensatory mechanism of increased nitric oxide synthase expresssion to further perpetuate parasite killing, indicating this cytokine is not paramount for host defense." (PMID 37375100, 2023). "In this sense, IL-2 may contribute to susceptibility or resistance in leishmaniasis, promoting activation of Th1 response as well as TNF which explains the strong correlation between these cytokines." (PMID 36017367, 2022). "Prospective studies and more participation on declaring existing cases in the adverse events notification system is required in order to assess the risk of leishmaniasis and other opportunistic diseases related to the use of anti TNF-α treatment more accurately." (PMID 31469834, 2019). "Consequently, loss of TNF significantly reduced the production of NO, resulting in fatal leishmaniasis." (PMID 29403488, 2018).
leishmaniasis (continued). "In agreement with our data, infection is a major adverse effect of immunosuppressive anti-TNFα treatment and reactivation of leishmaniasis or a higher susceptibility for an initial infection with Leishmania parasites has been linked to the application of several TNFα blockers by clinical reports." (PMID 30108591, 2018). "The issue of increased risk for leishmaniasis in the era of TNF-α antagonist therapy was recently acknowledged by the European Centre for Disease Prevention and Control and, considering the growing population receiving such treatment, the question undoubtedly deserves further elucidation." (PMID 31431985, 2018). "Thus, we suggest that anti-TNFα therapy using Cimzia® is potentially beneficial for patients living in high-risk areas of leishmaniasis." (PMID 30108591, 2018). "TNF- α is an important cytokine that induces nitric oxide synthase expression, promotes NO production and parasite death; however, evidence of persistent leishmaniasis caused by a strong inflammatory response induced by high TNF-α levels were reported." (PMID 22970332, 2012). "However, IL-6 has been strongly associated with leishmaniasis severity and deaths, which may be explained by TNF-α inhibition in early infection." (PMID 32966326, 2020). "Since increased L. major-induced gene-expression in C57BL/6 mice in comparison to BALB/c mice is associated with resistance and AhR-induced TNF is one known decisive agent in leishmaniasis, we wondered if susceptible mice could benefit from local AhR activation during early leishmaniasis." (PMID 31749794, 2019). "Most leishmaniasis cases occurring during treatment with TNF-α inhibitors were reported in the Mediterranean basin and in Brazil, where Leishmania infantum circulates." (PMID 40993715, 2025). "As these cell mechanisms affected by anti-TNF immunosuppression become clearer, more research is needed to improve the clinical management of these patients in endemic areas of leishmaniasis." (PMID 40808943, 2025). "The gene set in the low OBSCN expression allergic asthma group was primarily associated with Complement and coagulation cascades, NOD-like receptor signaling pathway, Leishmaniasis, TNF signaling pathway, and Neutrophil extracellular trap formation." (PMID 41458997, 2025). "TNF is shown to play an essential role in leishmaniasis pathogenesis and the outcome of the infection." (PMID 40594138, 2025). "Pro-inflammatory cytokines such as IL-1β, IL-6, TNF-α, and IFN-y have been associated with resistance in leishmaniasis." (PMID 38241360, 2024). "Seder and colleagues (2008) proposed a model for the development of the CD4+ Th1 response in leishmaniasis, which involved the expression of different combinations of three proinflammatory cytokines: IL-2, TNF-α, and IFN-γ." (PMID 38410517, 2024). "Further, the expression of key cytokines involved in leishmaniasis-mediated inflammation, including IL-1β, IL-10, IL-12 and TNF-α, remained constant across all experimental groups." (PMID 39076982, 2024). "Several studies have established that the development of Th1 responses, characterized by the production of cytokines such as TNF-α and IL-12, leads to the clearance of parasites and resistance to leishmaniasis." (PMID 39192975, 2024). "This study found that patients with leishmaniasis significantly increased TNF-α and decreased melatonin levels." (PMID 39199338, 2024). "Along this line, the combination of Pentoxifylline, a TNF inhibitor, plus MA showed promising results in Mucosal Leishmaniasis patients." (PMID 38787268, 2024). "In leishmaniasis, there are increased levels of proinflammatory mediators including TNF-α, CRP and adenosine deaminase." (PMID 39539349, 2024). "The enrichment analysis of the KEGG pathway revealed that 43 enriched categories were identified, of which 40 most significant categories, such as terpenoid backbone biosynthesis, TNF signaling pathway and leishmaniasis, are shown in." (PMID 35702766, 2023).